TNF (tumor necrosis factor)
Diseases named in the same sentence as TNF in open-access papers (continued):
Sharing a sentence is not in itself a finding about the gene and the disease.
Alexander disease (1 paper, 2022). Alexander disease (AxD) is a rare neurodegenerative disorder of the astrocytes comprised of two clinical forms: AxD Type I and Type II manifesting with various degrees of macrocephaly, spasticity, ataxia and seizures and leading to psychomotor regression and death. "Ablation of caspase-6 is correlated with low levels of the pro-inflammatory cytokines TNF-α and IL-6 and astroglial cl-caspase-6 has been found in brain samples of patients with Alzheimer’s and Alexander’s disease." (PMID 36347836, 2022).
altitude sickness (1 paper, 2023). Multiple symptoms associated with reduced oxygen at high altitude. "Plasma levels of IL-1β, IL-6, and TNF-α were found to be increased in individuals with altitude sickness compared to controls in low-altitude environments." (PMID 36891263, 2023).
amyloidoma (1 paper, 2024). Nodular localized form of amyloidosis with predominantly thoracic localization (pulmonary amyloidosis), considered as secondary protein structure disease in which insoluble protein fibrils accumulate extracellularly. "ALκ(TAL) amyloidomas had significantly more expression of monocyte chemoattractant protein-1 (MCP1; CCL2), and more expression of tumor necrosis factor-alpha trending towards significance (p=0.0627)." (PMID 39600710, 2024).
anaerobic bacterial infections (1 paper, 2017). "In the context of anaerobic bacterial infections, mRNA expression of IL1α, CXCL8, TNFα and human beta defensin (hBD)-2 were stimulated in keratinocytes by Propionibacterium acnes, an anaerobic bacterium." (PMID 28959685, 2017).
anal prolapse (1 paper, 2022). "Reduces anal prolapse, surrounding hyperemia by decreasing MPO activity, serum IL-1β, IL-6, TNF-α levels, and increasing IL-4, IL-10 levels." (PMID 35548468, 2022).
anal stenosis (1 paper, 2010). "Benign anal stenosis in the absence of previous surgery after successful treatment with anti-TNF-α agents has not previously been reported." (PMID 20659338, 2010).
and Soft Tissue Tumors (1 paper, 2012). "The combination of IL-4/GM-CSF/TL/TNF-α resulted in the greatest differentiation and maturation for DC-based immunotherapy for patients with bone and soft tissue tumors." (PMID 23300824, 2012).
anhidrosis (1 paper, 2025). Lack of sweating or the ability to sweat when provoked by the appropriate stimulus. "This aligns with known genotype–phenotype correlations in XLHED, where mutations affecting the TNF homology domain are typically associated with a more severe phenotype, including complete anhidrosis and marked dental anomalies." (PMID 41465157, 2025).
anxiety depression (1 paper, 2024). "At the same time, ZZCD could affect and participate in the process of neuroactive ligand/receptor interaction, regulate the HPA axis and secretion of prolactin and estrogen, and interfere with MAPK and TNF signaling pathways to reduce the level of inflammation to treat anxiety depression." (PMID 37905694, 2024).
aortic valve stenosis (1 paper, 2021). Aortic valve stenosis (AVS) is a condition characterized by narrowing of the heart's aortic valve opening. "In an animal model of IL-1Ra (interleukin-1 receptor antagonist) deficiency in mice an enflamed aortic valve stenosis was shown to occur, and TNF-α participated in the pathogenesis of valvular mineralization." (PMID 33318875, 2021).
asbestosis (1 paper, 2023). A lung disorder caused by inhalation of asbestos fibers. "In this context, it was noticed that TNF-α release from alveolar macrophages in patients with asbestosis, likely exposed to long fibers, was pivotal in the pathogenesis of the disease." (PMID 37894824, 2023).
Astigmatism (1 paper, 2023). A type of refraction error associated with abnormal curvatures on the anterior and/or posterior surface of the cornea. "Negative correlation included K1 with GSH/GSSG ratio, astigmatism axis with TNF-α, and CCT with IL-6." (PMID 36904299, 2023).
autoimmune bullous skin disease (1 paper, 2019). An autoimmune disease characterized by blisters on the skin. "Indeed, several case reports highlighted the occurrence of autoimmune bullous skin diseases under anti-TNF therapy." (PMID 31440247, 2019).
autonomic dysreflexia (1 paper, 2025). A syndrome associated with damage to the spinal cord above the mid thoracic level (see SPINAL CORD INJURIES) characterized by a marked increase in the sympathetic response to minor stimuli such as bladder or rectal distention. "Furthermore, the neuroinflammatory state underlying SCI leads to the release of soluble tumor necrosis factor-alpha (sTNFα), further contributing to autonomic dysreflexia and vascular tissue dysfunction." (PMID 40095463, 2025).
B-cell neoplasm (1 paper, 2019). A group of heterogeneous lymphoid tumors generally expressing one or more B-cell antigens or representing malignant transformations of B-lymphocytes. "A proliferation inducing ligand (APRIL), a member of the tumor necrosis factor (TNF) family, is involved in the pathogenesis of B cell neoplasms." (PMID 30999581, 2019).
bacterial endocarditis (1 paper, 2017). Endocarditis that is caused by an infection with a bacterial agent. "This case shows the risk of severe bacterial endocarditis from the initiation of TNF-α inhibitor therapy even in a small dose, probably due to drug-induced immunological insufficiency." (PMID 28179019, 2017). "We described a patient with lethal bacterial endocarditis after administration of TNF-α inhibitor, infliximab, for the treatment of psoriatic erythroderma." (PMID 28179019, 2017). "Lethal bacterial endocarditis was revealed after administration of tumor necrosis factor-α inhibitor, infliximab, for the treatment of psoriatic erythroderma." (PMID 28179019, 2017).
Barrett adenocarcinoma (1 paper, 2018). An adenocarcinoma arising from Barrett metaplastic epithelium in the esophagus. "The mechanism of action and up-regulation of TNF-α in the evolution of BE and Barrett’s adenocarcinoma from esophageal inflammation has been explained in other studies." (PMID 29449669, 2018).
Barth syndrome (1 paper, 2012). Barth syndrome (BTHS) is an inborn error of phospholipid metabolism characterized by dilated cardiomyopathy (DCM), skeletal myopathy, neutropenia, growth delay and organic aciduria. "Comparison of two anabolic growth mediators, IGF and GH, and two catabolic cytokines, IL-6 and TNF-α, in Barth Syndrome patients and healthy age-matched controls demonstrated a possible catabolic:anabolic imbalance in Barth Syndrome." (PMID 22721508, 2012). "Our results show that on average, the Barth Syndrome group possessed significantly lower (p = 0.02) TNF:GH ratios throughout their lives compared to the healthy controls with mean TNF:GH ratios of 0.004 and 0.019 respectively." (PMID 22721508, 2012). "We believe, further investigation into the role of TNF-α in Barth Syndrome cardiac and skeletal myopathies is warranted in a larger and more well-characterized group." (PMID 22721508, 2012).
Becker muscular dystrophy (1 paper, 2015). Becker muscular dystrophy (BMD) is a neuromuscular disease characterized by progressive muscle wasting and weakness due to degeneration of skeletal, smooth and cardiac muscle. "A recent study by our group showed that muscle inflammation is linked to the production of TNF-alpha-induced microRNAs that target the dystrophin mRNA and inhibit dystrophin translation in Becker muscular dystrophy patients." (PMID 26634117, 2015).
benign salivary gland tumors (1 paper, 2024). "Although the limited number of cases does not allow for a definitive cause-and-effect relationship, this raises the possibility of a link between TNF alpha activity and tumorigenesis in benign salivary gland tumors." (PMID 39684268, 2024).
bile duct sarcoma (1 paper, 2022). A sarcoma that involves the bile duct.
bladder disorders (1 paper, 2023). "By an elevated level of IL-1β or TNF-α, DV can be separated from these bladder disorders." (PMID 36983336, 2023).
blastomycosis (1 paper, 2013). Blastomycosis is a rare infection that may develop when people inhale a fungus called Blastomyces dermatitidis, a fungus that is found in moist soil, particularly where there is rotting vegetation. "In murine blastomycosis, macrophages were shown to use CR3 to recognize and ingest the BAD1 antigen and inhibit the TNF-α production required for host immunoprotection." (PMID 23382985, 2013).
blepharospasm (1 paper, 2023). "Our study found that the most common ocular adverse reactions caused by the five TNFα inhibitors were visual impairment and blurred vision, and the swelling of the eyelid and blepharospasm caused by certolizumab pegol was prominent." (PMID 37554981, 2023).
blood pressure (1 paper, 2022). "Curcumin also lowered adenine-induced high blood pressure, urinary albumin, the inflammatory cytokines interleukins 1 (IL-1) and 6 (IL-6), tumor necrosis factor α (TNF-α), cystatin C (CST3), and adiponectin (ADIPOQ)." (PMID 35910356, 2022).
bone marrow fibrosis (1 paper, 2021). "Observed cytokine regulation during fedratinib treatment, including downregulation of pro-inflammatory TNF-α, may contribute to improvements in MF symptoms, and upregulation of anti-inflammatory and anti-fibrotic adiponectin may affect bone marrow fibrosis." (PMID 32647323, 2021).
bordetellosis (1 paper, 2012). Any disease caused by infection with organisms of the genus Bordetella. "Consistent with published studies, TLR4def and TNF-α−/− mice inoculated with 105 CFU of RB50 quickly developed signs of lethal bordetellosis such as ruffled fur, hunched posture, decreased activity, and difficulty breathing, and succumbed 2 to 5 days post-inoculation." (PMID 22897969, 2012).
Bradycardia (1 paper, 2014). A slower than normal heart rate (in adults, slower than 60 beats per minute). "Here, we demonstrated that in chronically T. cruzi-infected C57BL/6 mice, anti-TNF ameliorated important signs of Chagas' heart disease, including bradycardia, prolonged P wave duration and PR interval, ART and AVB2, and remarkable CD features." (PMID 25140115, 2014).
brain abnormalities (1 paper, 2013). "Systemic inflammation was assessed with a composite measure of commonly used circulating inflammatory markers (C-reactive protein, CRP, and tumor necrosis factor-alpha, TNFα) that have been linked to brain abnormalities in community-based samples of older persons." (PMID 23991174, 2013).
breast cancer disease (1 paper, 2020). "In conclusion, the data of the present study indicate that TNF-α gene polymorphism is associated with breast cancer disease." (PMID 32102503, 2020). "Similarly, other studies conducted on Caucasian, Iranian, Turkish, Korean populations have not shown any correlation with TNF-α -308G/A and breast cancer disease." (PMID 32102503, 2020).
breast cyst (1 paper, 2016). A fluid-filled closed cavity or sac that is lined by an EPITHELIUM and found in the BREAST. "In conclusion higher levels of visfatin/NAMPT and TNF-α in the fluid from simple and complex breast cysts than in plasma suggest that their local production is related to inflammation." (PMID 27293305, 2016). "Contrary to leptin, resistin, and adiponectin, IL-6 levels were similar and the levels of visfatin/NAMPT and TNF-α in breast cyst fluid were significantly greater than in the circulation in both study subgroups." (PMID 27293305, 2016). "Contrarily, the levels of visfatin/NAMPT and TNF-α were significantly increased, and IL-6 levels were similar in the breast cyst fluid and plasma in both study groups." (PMID 27293305, 2016). "Contrarily, levels of visfatin/NAMPT and TNF-α in breast cyst fluid were significantly increased in relation to plasma in both study groups." (PMID 27293305, 2016). "Higher levels of visfatin/NAMPT and TNF-α in the fluid from simple and complex breast cysts than in plasma suggest that their local production is related to inflammation." (PMID 27293305, 2016). "However, contrary to this study we did not observe association between TNF-α and IL-6 in breast cyst fluids, but in accordance we found a negative association between TNF-α and estradiol levels." (PMID 27293305, 2016).
breast ductal carcinoma in situ (1 paper, 2022). "For example, favorable candidates for treatment may be patients diagnosed at the early stage of breast ductal carcinoma in situ, whose tumors express TNFα (about half of the patients)." (PMID 35663982, 2022).
capillary hemangioma (1 paper, 2019). A common hemangioma characterized by the presence of capillary-sized vascular channels without prominent epithelioid endothelial cells. "The authors report a case of lobular capillary hemangioma due to an anti-TNF-α drug." (PMID 31789263, 2019).
carbohydrate metabolism disorders (1 paper, 2024). "In diagnosing carbohydrate metabolism disorders, the use of adiponectin, TNF-α, IL-6, resistin, IL-1β and IL-23 in women, and IL-23 in men should be considered." (PMID 39769504, 2024).
cardiac aneurysms (1 paper, 2022). "Although extremely rare in paediatric BD, high dose glucocorticosteroids and cyclophosphamide are recommended for the management of pulmonary artery or cardiac aneurysms in the updated EULAR consensus, with escalation to TNF inhibitors for refractory cases." (PMID 35268369, 2022).
cat-eye syndrome (1 paper, 2024). Cat eye syndrome (CES) is a rare chromosomal disorder with a highly variable clinical presentation. "For PAN patients with early-onset, familial history or poor treatment response, testing for the cat eye syndrome chromosome candidate gene 1 and assessing ADA2 enzyme activity can assist in the diagnosis of DADA2 and facilitate timely treatment with tumor necrosis factor inhibitors." (PMID 39183419, 2024).
cat-scratch disease (1 paper, 2025). Cat scratch disease is an infectious illness caused by the bacteria bartonella (Bartonella henselae). "Bartonella hensalae, which causes cat scratch disease in humans, employs the effector BepD to activate STAT3 in a c-Abl kinase-dependent mechanism to suppress tumor necrosis factor-α signaling and stimulate IL-10 production." (PMID 40188438, 2025).
catalepsy (1 paper, 2013). A nervous system disorder characterized by diminished responsiveness and consciousness, and rigidity of the body. "Thus, in this study we attempted to investigate the effect of chronic administration of 8-OH-DPAT on 6-OHDA-induced catalepsy and possible involvement of TNF-α, IL-1β and IL-6." (PMID 24570834, 2013). "The role of pro-inflammatory cytokines in the pathogenesis of PD has been shown in several studies, although the effect of chronic administration of 5-HT1A receptor agonists on 6-OHDA-induced catalepsy and the role of cytokines such as TNF-α, IL-1β and IL-6 has not been clearly studied yet." (PMID 24570834, 2013).
cervical disc degeneration (1 paper, 2014). "Based on our data, IL-1β, IL-1R as well as TNF-α might be involved in the pathogenesis of cervical disc degeneration, where IL-1β and IL-1 R might act as better therapeutic targets." (PMID 24804684, 2014).
chalazia (1 paper, 2025). "Additionally, one case report described the development of large bilateral chalazia after bortezomib therapy and indicated that TNF promotion was a possible contributing factor." (PMID 40709135, 2025).
Charcot foot (1 paper, 2015). "Moreover, in the acute Charcot foot, inflammatory modulation of peripheral monocytes with increased spontaneous and induced production of TNF-α has been noted." (PMID 26137498, 2015).
Chronic diarrhea (1 paper, 2025). The presence of chronic diarrhea, which is usually taken to mean diarrhea that has persisted for over 4 weeks. "Chronic diarrhea in IBD results from intestinal barrier dysfunction, increased permeability, and electrolyte absorption impairment, all of which are exacerbated by pro-inflammatory cytokines such as TNF-α and IL-6." (PMID 40299351, 2025).
chronic leukemia (1 paper, 2022). A slowly progressing leukemia characterized by a clonal (malignant) proliferation of maturing and mature myeloid cells or mature lymphocytes. "It has been shown that, in patients with chronic leukemia, there is an increase in the expression of L-selectin on neutrophils, which may be due to a high level of TNF-α in the blood serum." (PMID 36362436, 2022).
Chronic tubulointerstitial nephritis (1 paper, 2025). Chronic inflammation of the kidney affecting the interstitium of the kidneys surrounding the tubules. "Persistent infection triggers a prolonged inflammatory response, with elevated levels of pro-inflammatory cytokines such as interleukin-6 (IL-6) and tumor necrosis factor-alpha (TNF-α), leading to chronic tubulointerstitial nephritis." (PMID 40400807, 2025).
cicatricial alopecia (1 paper, 2024). Scarring hair loss, also known as cicatricial alopecia, is the loss of hair which is accompanied with scarring. "Characteristics of eligible studies utilizing tumor necrosis factor-alpha inhibitors for the cicatricial alopecia treatment." (PMID 38335182, 2024). "Characteristics of eligible studies with tumor necrosis factor inhibitors treatment induced cicatricial alopecia." (PMID 38335182, 2024).
Clear cell carcinoma (1 paper, 2016). "Clear cell carcinoma cells also produce high levels of IL-6 and other TNF network members (our unpublished data)." (PMID 26871292, 2016).
cleft lip (1 paper, 2021). Congenital defect in the upper lip where the maxillary prominence fails to merge with the merged medial nasal prominences. "The consistent expression of IL-2,6,13 and TNF-α in the cleft lip and palate affected tissue indicates the role of these cytokines in the pathogenesis of these anomalies." (PMID 33673258, 2021).
CNS leukemia (1 paper, 2026). "CNS leukemia-associated seizures are primarily driven by blood-brain barrier (BBB) disruption following leukemic infiltration, which triggers a neuroinflammatory cascade involving pro-inflammatory cytokines such as IL-6 and TNF-α, and impairs glutamate homeostasis." (PMID 41977486, 2026).
coal worker pneumoconiosis (1 paper, 2023). "In vitro experiments have demonstrated that IL-1β and TNF-α secretion by alveolar macrophages is considered an early inflammatory response that leads to progressive tissue damage and fibrosis in coal worker pneumoconiosis (CWP)." (PMID 36675056, 2023).
cocaine use disorder (1 paper, 2022). A substance-related disorder that involves the recurring use of cocaine despite negative consequences. "Levels of pro−inflammatory cytokines, IL−1β, TNF−α and IL−6, are elevated in humans with cocaine use disorder." (PMID 35954251, 2022).
complement over activation (1 paper, 2020). "Our results suggest that acadesine suppresses TNF-α induced C3, likely through an AMPK-independent pathway, and could have potential use in complement over activation diseases." (PMID 33362238, 2020).
conduction disorders (1 paper, 2019). "In spite of several studies investigating the impact of anti-TNF-α drugs on heart failure and atherogenesis associated with chronic rheumatoid diseases, little is known about the impact of these drugs on conduction disorders." (PMID 30942280, 2019).
congenital Zika syndrome (1 paper, 2022). "Similarly, babies with congenital Zika syndrome were found to be highly associated with single nuclear polymorphisms in TLR-3 or TNF-α (tumor necrosis factor-alpha) alleles." (PMID 36615782, 2022).
Conn’s syndrome (1 paper, 2010). "After adrenalectomy, the levels of the soluble forms of TNF α decreased in patients with Conn’s syndrome." (PMID 20640152, 2010). "After adrenalectomy, the blood concentrations of TNF α R1 and TNF α R2 were decreased in patients with Conn’s syndrome." (PMID 20640152, 2010). "The concentrations of TNF α were significantly elevated in patients with malignant tumors of the adrenal cortex and in patients with Conn’s syndrome compared to control." (PMID 20640152, 2010).